ZEB1 (zinc finger E-box binding homeobox 1)
Diseases named in the same sentence as ZEB1 in open-access papers (continued):
Sharing a sentence is not in itself a finding about the gene and the disease.
breast carcinoma (continued). "Together, these results indicated that CLDN4 is a direct GRHL2 target while CDH1, ZEB1, or ZEB2 are unlikely to represent direct GRHL2 target genes in luminal breast cancer cells." (PMID 36691073, 2023). "Non-CSCs in human basal breast cancers, for example, can acquire CSC phenotypes when zinc finger e-box binding homeobox 1 (ZEB1) is activated." (PMID 36890838, 2023). "Among EMT-related genes, direct regulation of CLDN4 is corroborated but several targets identified in other cells (including CDH1 and ZEB1) are ruled out by both ChIP- and Bru-seq as being directly controlled by GRHL2 in luminal breast cancer cells." (PMID 36691073, 2023). "We do not detect GRHL2 binding sites in ZEB1 or ZEB2, across all the luminal and basal A breast cancer cell lines we have analyzed, which contrasts with previous findings in other cell types." (PMID 36768838, 2023). "Our previous work showed that expressions of some mesenchymal genes do not require ZEB1 activation and that the high expression of a group of EMT genes positively controlled by ZEB1, but not TGF-β, is correlated with better prognosis of breast cancer patients." (PMID 36900269, 2023). "ZEB1 is canonically repressed by GRHL2 in a negative feedback loop in multiple cancer types, including breast cancer, bladder cancer, and ovarian cancer." (PMID 37761927, 2023). "In breast cancer and OSCC cells, expression profiles of ZEB1/2 and Snail are not positively correlated with each other and those of Ets1/2 levels." (PMID 35451213, 2022). "Supporting this, human basal breast cancer cells switch between non-CSC and CSC states depending on the expression of the EMT inducer Zinc Finger E-Box Binding Homeobox 1 (ZEB1)." (PMID 36612206, 2022). "In breast cancer, inhibiting EMT by overexpressing miR‐200, a well‐known microRNA that directly targets ZEB1/2, does not affect lung metastasis, but contributes to recurrent lung metastasis after chemotherapy." (PMID 35451213, 2022). "Although ZEB1 and VIM were not distinctly upregulated, the overall EMT program was higher in resistant cells than in sensitive breast cancer cells." (PMID 34316714, 2021). "Intriguingly, we discovered a negative correlation between ZEB1 and DNAJB9 protein levels in 75 breast cancer tissue samples (R = −0.09855; p < 0.0001)." (PMID 33966034, 2021). "Taken together, these results revealed that FBXL10 physically interacted with SNAI1 in breast cancer cells, but not SLUG or ZEB1." (PMID 34718323, 2021). "In breast cancer, GRHL2 acts as an EMT suppressor by forming a double-negative feedback loop with the EMT driver ZEB1 via the miR-200 family." (PMID 32266287, 2020). "In conclusion, our results showed that high ZEB1 protein expression was a negative predictive marker of pCR and DFS in neoadjuvant therapy in breast cancer patients and in HorR-positive and HER2-overexpressing subgroups." (PMID 30976202, 2019). "Our results showed that high ZEB1 protein expression was a negative predictive marker of pCR and DFS in neoadjuvant therapy in breast cancer patients and in HorR-positive and HER2-overexpressing subgroups." (PMID 30976202, 2019). "Our research demonstrated that ZEB1 expression is an independent negative predictive factor of pCR and a prognostic biomarker of DFS in HorR-positive and HER2 overexpressing breast cancer patients." (PMID 30976202, 2019). "In contrast, the epithelial breast cancer and fibrotic cell lines MCF7 and MCF10A showed high E-cad levels and low levels of ZEB1, CD44s and HAS2, reflecting a weak or absent EMT signature." (PMID 28086235, 2017). "LBX1 directly up-regulates ZEB1, ZEB2, Snail and TGFB2 but not Twist1 and promotes breast cancer cell migration, implying a role as a master regulator of EMT." (PMID 26797644, 2016). "We showed that when human mammary tumor cells express GPC3, the canonical Wnt pathway is inhibited, the transcription factors ZEB1 is downregulated and the key marker of epithelial phenotype E-Cadherin is upregulated." (PMID 27507057, 2016).
breast carcinoma (continued). "We here demonstrate that the expression of ZEB1 and BMP-inhibitors is correlated with bone metastasis, but not with brain or lung metastasis of breast cancer patients." (PMID 25973542, 2015). "In contrast, only 11.1% of the non basal breast cancer cell lines expressed LPAR1 and none expressed ZEB1 above the corresponding overall means." (PMID 26098771, 2015). "As opposed to LPAR1, we did not observe significant correlations between ZEB1 and LPAR2 or LPAR3 in publicly available breast cancer cell line databases." (PMID 26098771, 2015). "Scatter plot analysis for LPAR1 and ZEB1 correlation in the non basal and basal breast cancer cell lines highlights the fact that LPAR1 and ZEB1 expression correlates significantly in the basal but not in the non-basal subtypes." (PMID 26098771, 2015). "For example, miR-200a, miR-200b and miR-429 comprise a double-negative feedback loop with the transcription repressors ZEB1 and SIP1 in breast cancer cells." (PMID 26418018, 2015). "Taken together, these results indicated that in addition to vimentin, MTHFD2 depletion reduced N-cadherin expression but did not significantly modulate ZEB1, ZEB2 and SLUG transcription in MDA-MB-231(SA) breast cancer cells." (PMID 23295955, 2013). "GRHL2 is lost in more mesenchymal-like breast cancers, such as TNBC and claudin-low, suggesting that signaling converging on ZEB1 and miR-200c are important not just for EMT, but also for anoikis." (PMID 23185507, 2012). "Together, this data indicates that CDH1, ZEB1, and ZEB2 genes do not represent direct transcriptional targets of GRHL2 in luminal breast cancer and their regulation may occur through post-transcriptional regulation in this cellular context." (PMID 36691073, 2023). "Furthermore, as opposed to ZEB1, SNAI1 is equally expressed in basal-like breast cancers with partial-EMT and post-EMT features." (PMID 38111531, 2023). "In a study conducted for primary breast cancer, 77 (18.0%) of 427 primary breast cancer patients were found to have EMT-CTCs characterized by TWIST, SNAIL1, SLUG, and ZEB1 expression levels, and patients without EMT-CTCs had a longer disease-free survival than those with EMT-CTCs." (PMID 33266262, 2020). "However, ZEB1 was not the major inducer of EPB41L5 in tongue SCC, unlike in breast cancer and renal cancer." (PMID 27871329, 2016). "We found that neither the luminal A breast cancer cell line (MCF7) or the type 1 endometrial cancer cell line (Ishikawa) express FN1 or MSN, consistent with their pre-EMT phenotype, indicated by expression of E-cadherin and lack of ZEB1." (PMID 21501518, 2011). "Indeed, OPG upregulation promoted the pro-metastatic processes EMT and stemness in the non-carcinogenic (MCF-10A) and luminal breast cancer (T-47D, MCF-7) cells, through upregulating the mesenchymal (N-cadherin, SNAIL and ZEB1) and stemness (CD44, ALDH1, Nanog, Klf-4 and Sox2) markers." (PMID 39181873, 2024).
pancreatic cancer (253 papers, 2010 to 2026). "Metastasis key molecule ZEB1 is believed to mediate EMT-associated ferroptosis sensitivity in pancreatic cancer cells by regulating lipogenic enzyme expression and phospholipid composition." (PMID 39827156, 2025). "The expression of ZEB1 is strongly associated with the resistance of cancer cells to chemotherapeutic agents including gemcitabine, 5-fluorouracil, and cisplatin in pancreatic cancer cells." (PMID 38613804, 2024). "In pancreatic cancer, however, treatment of MiaPaCa-2 cells with gemcitabine caused an upregulation of the ZEB1 protein through alternative polyadenylation of the transcript." (PMID 37705830, 2023). "To further explore the underlying mechanism of ZEB1 O-GlcNAcylation induced mesenchymal pancreatic cancer cell ferroptosis sensitivity, we firstly assessed the lipid metabolism associated enzymes expression level." (PMID 35844792, 2022). "ZEB1 is significantly associated with poorly differentiated pancreatic tumors and can suppress the expression of stemness-inhibiting miR-200 family members and miR-203, resulting in the induction of the EMT program and maintenance of stemness." (PMID 34453639, 2021). "Both tumor-associated stroma and pancreatic cancer cells demonstrated a great level of Zeb-1 expression, which was linked with poor prognosis in PDAC patients." (PMID 33918146, 2021). "ZEB1 deficient pancreatic cancer cell lines are incapable of compensatory increasing glycolysis when oxidative phosphorylation is blocked, highlighting poor glycolytic reserve." (PMID 34459003, 2021). "EMT in pancreatic cancer can be visualized by disseminated tumor growth, loss of cytokeratins, or expression of the mesenchymal transcription factors Zeb1 or nuclear β-Catenin 19,20,27." (PMID 35003368, 2021). "Our results suggest that the high expression of phosphorylated ROCK2 causes ZEB1-mediated gemcitabine resistance in pancreatic cancer cells." (PMID 31783584, 2019). "Regarding the types of tumors, our study indicated that high expression of ZEB-1 was also significantly associated with worse OS in colorectal cancer, esophageal squamous cell carcinoma, pancreatic cancer, gastric cancer and hepatocellular carcinoma." (PMID 31248382, 2019). "Our data demonstrate that embelin can inhibit/reverse pancreatic tumor metastasis by inducing the expression of E-cadherin and inhibiting its associated transcription factors (Snail, Slug, and ZEB1) and MMPs (MMP-2 and MMP-9)." (PMID 24694877, 2014). "This cadherin switch was also associated with increased Twist, Snail, Zeb1, and Zeb2 expression, findings that are reminiscent of those observed in pancreatic cancer cells under hypoxic conditions." (PMID 21887310, 2011). "An increasingly recognized feature of EMT and CSC is resistance to anticancer agents, and ZEB1 has been implicated in drug resistance of pancreatic cancer cells." (PMID 24281177, 2010). "Several studies have shown an association of ZEB1 expression with resistance to drugs used to treat pancreatic cancer." (PMID 24281177, 2010). "Interestingly, there is a positive correlation between elevated Zeb-1 expression in the tumor-associated stroma and pancreatic cancer cells and a poor prognosis for individuals with PDAC." (PMID 39087024, 2024). "Moreover, ZEB1 expression is associated with poor clinical outcomes in solid tumors (including breast, colorectal, and pancreatic tumors), and poor prognosis and survival in various tumor types." (PMID 36076302, 2022). "Interestingly, this study also showed that Zeb1 deletion causes a suspension of invasion and metastasis of pancreatic tumor cells." (PMID 34768901, 2021). "Our results indicated that over-expression of miR-675-5p could inhibit cell migration and invasion of pancreatic cancer which was closely associated with the EMT related protein ZEB1." (PMID 28212565, 2017).
pancreatic cancer (continued). "Specifically, ZEB1 was found to be significantly associated with poor OS for pancreatic cancer, gastric cancer and colorectal cancer patients, while ZEB2 was found to be significantly associated with poor OS for hepatocellular carcinoma and gastric cancer patients." (PMID 28416756, 2017). "In summary, our current findings implicated an extracellular acidic microenvironment-miR-652/ZEB1-EMT axis which might involve in tumorigenesis of pancreatic cancer." (PMID 26498682, 2015). "ZEB1 has also been shown to be associated with drug resistance of pancreatic cancer cells." (PMID 24281177, 2010). "Finally, ZEB1-driven phenotypic plasticity of epithelial pancreatic cancer cells was also observed in vivo, where differentiated primary tumor cells underwent dedifferentiation associated with an upregulation of ZEB1 at the invasive front, resulting in liver metastasis." (PMID 32266287, 2020). "Recent studies and experimental models have disclosed that EMT in pancreatic cancer is mostly triggered by Zeb1, promoting cell plasticity and playing a key role in early dissemination of PDAC." (PMID 41481650, 2026). "Our study found that ZEB1 is overexpressed at both the mRNA and protein levels in pancreatic cancer tissue, whereas ZEB2 was characterized by lower mRNA and higher protein levels." (PMID 41481650, 2026). "LncRNA XIST boosts ZEB1 expression through competitively binding to miR-429, and contributes to pancreatic cancer cell EMT." (PMID 40703656, 2025). "LncRNA IUR, on the other hand, enhances miR-200 expression, thereby suppressing ZEB1 expression and inhibiting pancreatic cancer cell migration and invasion." (PMID 40703656, 2025). "miR-200c-5p, for instance, is a well-characterized suppressor of ZEB1/ZEB2, and its downregulation is associated with EMT activation in pancreatic cancer." (PMID 40728965, 2025). "CircUBAP2 was upregulated in pancreatic cancer tissues, which enhances the expression of the key downstream gene, Zeb1, through the inhibition of hsa-miR-494." (PMID 40109856, 2025). "In pancreatic cancers, glucose-activated O-GlcNAc modification of ZEB1 at Ser555 enhances its stabilization and nuclear translocation, thus decreasing lipid peroxidation and ferroptosis in mesenchymal pancreatic cancer cells." (PMID 41059334, 2025). "Blocking ZEB1 reverses chemoimmunotherapy resistance in pancreatic cancer by boosting CD8+ T cells, reducing neutrophils, and enhancing tumor-killing immune responses." (PMID 40924501, 2025). "MSI2 also facilitates EMT in pancreatic cancer induced by EGF through the ZEB1-ERK/MAPK signaling pathway." (PMID 39097735, 2024). "In studies of pancreatic cancer, CDK8 was found to activate the expression of factors critical for stimulating the EMT process (Snail1 and ZEB1) through the Wnt/β-catenin signaling pathway and to increase the invasion and migration of pancreatic cancer cells." (PMID 38460002, 2024). "In pancreatic cancer, EMT is associated with metastasis and gemcitabine resistance, which depends on the expression of ZEB1 and vimentin." (PMID 39201656, 2024). "Regulatory relationship between EPLIN and several key regulators of EMT, namely SNAIL, SLUG and ZEB1 in pancreatic cancer was also demonstrated." (PMID 39730634, 2024). "For example, ZEB1 promotes the migration of CSCs by suppressing repressive stemness microRNAs in pancreatic cancer cells." (PMID 38555451, 2024). "Aberrant expression of ZEB1 has been detected in a wide range of cancer types, such as cervical cancer, pancreatic cancer, osteosarcoma, lung cancer, liver cancer, stomach cancer, colorectal cancer, and breast cancer." (PMID 38613804, 2024). "Examination of human tissue specimens and pancreatic cancer cell lines revealed a connection between Zeb-1 and the expression of E-cadherin." (PMID 39087024, 2024). "ZIP4 also induces the expression of ZEB1, suppressing the expression of ZO-1 and Claudin-1 to induce migration and invasion in pancreatic cancer." (PMID 39664563, 2024).
pancreatic cancer (continued). "ZEB1 is expressed heterogeneously in the TME of both human and murine tumors, and high expression of ZEB1 in stromal cells of pancreatic cancer is a prognostic factor for poor survival in patients." (PMID 38937629, 2024). "MSI2 also promotes EMT induced by EGF in pancreatic cancer through the ZEB1-ERK/MAPK signaling pathway." (PMID 39097735, 2024). "In vivo study of pancreatic cancer supports that ZEB1 is essential for tumor invasion and metastasis." (PMID 38543112, 2024). "Collective data show that ZEB1/2 expression in breast, colorectal, and pancreatic cancers affects poor patient outcomes." (PMID 38543112, 2024). "Mocetinostat, an HDAC inhibitor, inhibits the EMT activator ZEB1, suppressing drug resistance in lung and pancreatic cancer." (PMID 39201656, 2024). "VASH2 increased the expression of ZEB1/2 in pancreatic tumors through activation of the SHH pathway, which both facilitated the EMT process and increased the resistance of pancreatic tumors to gemcitabine chemotherapy." (PMID 37821528, 2023). "In mesenchymal pancreatic cancer cells, increased O-GlcNAc level induced by high glucose influx leads to ZEB1 O-GlcNAcylation and promotes cancer cell ferroptosis sensitivity." (PMID 37838167, 2023). "A further study using another pancreatic cancer model demonstrated that ZEB1 promoted the invasion and metastasis of cancer cells and the depletion of ZEB1 suppressed EMT-related cancer promoting changes." (PMID 36766756, 2023). "In KP4 high-mesenchymal state pancreatic cancer cells, ZEB-1 knockdown prevented the cells from GPX4-inhibitor-induced cell death." (PMID 37046995, 2023). "Of functional relevance, ZEB1-expressing CAFs stimulated RAS activity in pancreatic cancer cells, supporting their migration, invasion and proliferation." (PMID 37174079, 2023). "There were minimally significant differences in VIP expression between normal and pancreatic cancer tissue (p = 0.012) and increased ZEB1 expression in cancer tissue." (PMID 37444395, 2023). "Accumulating evidence in pancreatic cancer has demonstrated that ZEB1 regulates the EMT process, driving the transformation of cancer cells into CSCs with self-renewal properties." (PMID 37853437, 2023). "Several observations have identified ZEB1 as a regulator in pancreatic Kras-driven carcinogenesis, demonstrating that Zeb1 deletion in the KPC mouse model significantly delayed the onset of pancreatic cancer with a remarkably low number of α-SMA+ fibroblasts." (PMID 37174079, 2023). "Our work also suggests a mechanism for O-GlcNAc modification ZEB1 involving the regulation of glycolipid metabolism as crucial process in mesenchymal pancreatic cancer cell ferroptosis." (PMID 35844792, 2022). "Overexpression of ZEB1 leads to the progression of multiple cancers, including gastric carcinoma, pancreatic cancer, and colorectal cancer." (PMID 36168636, 2022). "LncDYNC2H1-4 can facilitate pancreatic cancer EMT as a sponge for miR-145 to mediate the repression of ZEB1, which has been identified as a direct target of miR-145." (PMID 35819532, 2022). "In pancreatic cancer, ZEB1 has been identified as a critical factor of cell plasticity, and one that advances metastasis." (PMID 35345586, 2022). "Taken together, these results indicated that ZEB1 O-GlcNAcylation regulated lipid metabolism contributed to ferroptotic treatment strategy in pancreatic cancer in vivo." (PMID 35844792, 2022). "In order to reveal the linc00511 function in DET-mediated proliferation and metastasis inhibition, the mRNA level of p21, Snail, and ZEB1 in DET combined si-linc00511-1 treatment pancreatic cancer cells was tested by qRT-PCR." (PMID 35794978, 2022). "Numerous studies had disclosed the relationship between MAPK signal pathway and EMT, such as Musashi2 promotes EMT in pancreatic cancer through ZEB1-ERK/MAPK, Integrin/EGFR-ERK/MAPK, and ERK/MAPK signaling pathway." (PMID 35898472, 2022).